SLC2A2 (solute carrier family 2 member 2)
Description:
Facilitative hexose transporter that mediates the transport of glucose, fructose and galactose. Likely mediates the bidirectional transfer of glucose across the plasma membrane of hepatocytes and is responsible for uptake of glucose by the beta cells; may comprise part of the glucose-sensing mechanism of beta cells. May also participate with the Na(+)/glucose cotransporter in the transcellular transport of glucose in the small intestine and kidney. Also able to mediate the transport of dehydroascorbate and urate.
Synonyms: GLUT-2; GLUT2
Tractability: Small molecule: a high-quality ligand is known. Antibody: UniProt places it where antibodies can reach, with high confidence; its Gene Ontology location is reachable by antibodies, with high confidence; UniProt predicts a signal peptide or a membrane-spanning region; the Human Protein Atlas places it where antibodies can reach. PROTAC: its protein half-life has been measured; a small molecule that binds it is known.
Target class: SLC superfamily of solute carriers; Electrochemical transporter; SLC02 family of hexose and sugar alcohol transporters; Transporter
Gene: Protein-coding gene on chromosome 3 (170,995,125 to 171,026,775, reverse strand). Ensembl gene ENSG00000163581.
Subcellular location: Cell membrane
Subcellular location (Human Protein Atlas): Mid piece; Plasma membrane; Principal piece
Pathways (Reactome):
Developmental Biology: Regulation of gene expression in beta cells
Digestion and absorption: Intestinal hexose absorption
Disease: Defective SLC2A2 causes Fanconi-Bickel syndrome (FBS)
Metabolism: Regulation of insulin secretion
Transport of small molecules: Cellular hexose transport
Gene Ontology:
Molecular function: D-glucose transmembrane transporter activity; dehydroascorbic acid transmembrane transporter activity; fructose transmembrane transporter activity; galactose transmembrane transporter activity; hexose transmembrane transporter activity; transmembrane transporter activity
Biological process: D-glucose transmembrane transport; dehydroascorbic acid transport; fructose transmembrane transport; galactose transmembrane transport; carbohydrate metabolic process; positive regulation of insulin secretion involved in cellular response to glucose stimulus; transmembrane transport
Cellular component: plasma membrane; apical plasma membrane; brush border; membrane; cell-cell junction; cytoplasm
Genetic constraint (gnomAD): Loss-of-function variants: 27 observed, 43.38 expected, observed/expected ratio (o/e) 0.62, 90% interval 0.46 to 0.86. The upper end of that interval is the gene's LOEUF score, 0.86, which puts it in group 3 of 6, group 1 being the genes least tolerant of losing a copy. Missense variants: 486 observed, 591.48 expected, observed/expected ratio (o/e) 0.82, 90% interval 0.76 to 0.89. Synonymous variants: 201 observed, 213.28 expected, observed/expected ratio (o/e) 0.94, 90% interval 0.84 to 1.06.
Homologues: Orthologues: chimpanzee SLC2A2 (99% identical), macaque SLC2A2 (98% identical), pig SLC2A2 (87% identical), dog SLC2A2 (86% identical), guinea pig SLC2A2 (84% identical), rat Slc2a2 (82% identical), mouse Slc2a2 (82% identical), rabbit SLC2A2 (81% identical), tropical clawed frog slc2a2 (63% identical), zebrafish slc2a2 (58% identical), Caenorhabditis elegans fdgt-1 (34% identical), Drosophila melanogaster sut1 (29% identical), and 40 more. Paralogues in human: SLC2A1 (52% identical), SLC2A4 (52% identical), SLC2A3 (48% identical), SLC2A14 (47% identical), SLC2A5 (38% identical), SLC2A7 (34% identical), SLC2A11 (30% identical), SLC2A9 (30% identical), SLC2A13 (28% identical), SLC2A12 (27% identical), SLC2A10 (24% identical), SLC2A8 (24% identical), and 1 more.
Diseases named in the same sentence as SLC2A2 in open-access papers:
SLC2A2 is named in the same sentence as 144 diseases in open-access papers, as found by Europe PMC text mining. Sharing a sentence is not in itself a finding about the gene and the disease. The quoted sentences say what the papers report.
diabetes (163 papers, 2007 to 2026). "Mechanistically, in diabetes, β cells degenerate from their mature differentiated state to a dedifferentiated state through the downregulation of β‐cell‐enriched genes, such as Glut2 (Slc2a2), Pdx1, and Mafa, but the underlying mechanism remains less clear." (PMID 40539402, 2025). "During diabetes treatment, the C-allele of rs8192675 in SLC2A2 has been found to regulate the action of metformin and reduce the absolute level of HbA1c more effectively than the T-allele." (PMID 39535164, 2024). "Its role in human islets has been questioned, but SLC2A2 mutations cause transient neonatal diabetes." (PMID 36656641, 2023). "This would suggest that lower SLC2A2 expression would increase the risk of development of diet-induced diabetes as we age." (PMID 37717665, 2023). "The reported variant, c.589G>A p.Val197Leu (in SLC2A2) has been in discussion since its first description as it was also reported in heterozygous state in African American women with diabetes mellitus (DM)." (PMID 36692815, 2023). "Downregulation of SLC2A2 is associated with not only T2D but also neonatal diabetes and early childhood diabetes, suggesting a likely role in insulin secretion." (PMID 35788821, 2022). "We previously showed that single nucleotide polymorphisms (SNPs) found at the SLC2A2 locus, that result in reduced SLC2A2 gene expression, are associated with increased glycaemic response to the major diabetes therapeutic, metformin." (PMID 32938474, 2020). "In a study comprising 104 patients with diagnosed transient (n = 25) or permanent (n = 79) neonatal diabetes, 5 patients were found to carry a homozygous SLC2A2 mutation." (PMID 32394191, 2020). "There are reports about transient neonatal diabetes occurring in patients with a homozygous SLC2A2 mutation." (PMID 32394191, 2020). "Intriguingly, most of the identified genes, which showed strong signals in normal islets but were potently suppressed by STZ, were previously linked with important β-cell functions or diabetes development, such as Slc2a2, Ucn3, Gad1, Cox6a2, Trpm6 and Vdr." (PMID 23828045, 2013). "In contrast, a SLC2A2 homozygous variant was found in a single patient, setting the frequency of recessive mutations of Group 1 to 1.7% (1/58) or 4.5% (1/22) when considering the subgroup of patients with mute family history of diabetes." (PMID 36178555, 2023). "Notably, most of the downregulated genes have been implicated in diabetes pathogenesis; SLC2A2 (Glut2) is involved in β-cell function and insulin secretion." (PMID 25379510, 2014). "STZ treatment also suppressed expression of a wide range of genes linked with key β-cell functions or diabetes development, such as G6pc2, Slc2a2 (Glut2), Slc30a8, Neurod1, Ucn3, Gad1, Isl1, Foxa2, Vdr, Pdx1, Fkbp1b and Abcc8, suggesting global β-cell defects in STZ-treated islets." (PMID 23828045, 2013). "We recently produced renal Slc2a2 (also known as Glut2) knockout mice, which show massive glycosuria and are protected from diabetes and diet-induced obesity." (PMID 39082939, 2024). "In this study, we aimed to confirm a direct mechanistic role for SLC2A2 underpinning these genetic observations, by reducing whole-body and intestinal levels of Slc2a2 in pre-clinical mouse models of diabetes and exploring metformin responses." (PMID 37717665, 2023). "Other established regulators of beta cell function and genes involved in monogenic diabetes or T2D risk were identified among the screening hits, such as NKX2.2, SLC2A2, PPP1R15B and IGF2 28–35." (PMID 36543916, 2023). "Dietary habits influence the association of six genes (C2CD4B, CDKN2B, GIPR, HHEX, SLC2A2, and SLC30A8) forming the third cluster with diabetes, adipogenesis, and cardiovascular risk." (PMID 36982283, 2023).
diabetes (continued). "Our list is supported by colocalization of genes known to lead to Mendelian forms of diabetes (e.g., SLC2A2 and WFS1) and of genes with previously demonstrated mechanisms of association with IR/T2D (e.g., METAP2, PLEKHA1 [TAPP1], FAM13A, and KLF14)." (PMID 35292083, 2022). "Homozygous whole-body Slc2a2 knockout mice, in contrast, develop diabetes-like symptoms including hyperglycemia and increased circulating free fatty acid levels early after birth and usually die before weaning age." (PMID 32591906, 2020). "GLUT2-null mice and mice expressing Slc2a2 siRNA in β-cells displayed all the major traits of human diabetes mellitus." (PMID 32394191, 2020). "Transgenic mice with β-cell–targeted overexpression of HIF-1 by deletion of the Vhl gene exhibited reduced expression of Pdx1, Mafa, and Slc2a2 genes when they developed diabetes." (PMID 25503986, 2014). "For instance, the inhibition of Glut2 (Slc2a2) dynamics has the potential to improve diabetes mellitus in mice, and Slc7A5, a glutamine antiporter, could be an attractive target for therapy-resistant, KRAS-mutant colorectal cancer in mice." (PMID 36787192, 2023). "Interestingly, at least 12 genes including SLC2A2, G6PC2, SLC30A8, PCSK1 and RAPGEF4, also overlap with previously implicated genes from genome wide association studies (GWAS) for type 2 diabetes mellitus and blood glucose loci." (PMID 31682591, 2020). "Interestingly, some ATAC-seq peaks overlapping with both these marks are annotated to genes that have islet specific function and/or have been associated with diabetes by GWAS e.g., TCF7L2, SLC2A2, FOXO1 and HNF1B27." (PMID 31123324, 2019). "At 3 months, fructose feeding induced upregulation of several genes coding nuclear factors (Rxrg, Nr1h3, p≤0.1), proteins involved in lipid metabolism including Pltp (p≤0.1), Lcat, and Cd36 (p≤0.05), cell death inflammation (Tnf, p≤0.1), and diabetes (Irs1, Slc2a2, p≤0.1)." (PMID 25380250, 2014). "Likewise, down-regulation of Irs2 and the glucose transporter GLUT2 (Slc2a2) in pancreatic islets confirms previous reports and reflects deterioration of beta cell function in the course of insulin resistance and diabetes." (PMID 18590522, 2008). "In this review, we discuss the physiological roles of GLUT2 and the pathophysiology of mutants, highlight all of the previously reported SLC2A2 mutations associated with dysglycaemia, and review the potential molecular mechanisms leading to dysglycaemia and diabetes mellitus in FBS patients." (PMID 32877990, 2020). "This suggests that the reduced expression of Slc2a2 may not necessarily be the limiting step that leads to diabetes in Hnf1a deficiency." (PMID 27667715, 2016). "Studies have shown that EDEM2 silencing decreases SLC2A2 and PXD1 expression, leading to impaired insulin secretion, and that it is involved in early childhood diabetes." (PMID 39535371, 2025). "In both T1D and T2D, we found enrichment of monogenic forms of diabetes, as expected —2 genes in T1D (RASGRP1, INS) and 8 in T2D (HNF1B, GCK, WFS1, KCNJ11, ABCC8, HNF1A, PPARG, SLC2A2)." (PMID 33836063, 2021). "Using a mouse model of diabetic pregnancy, we have shown that maternal hyperglycemia, through high rates of glucose transport into embryo cells via the high KM glucose transporter, GLUT2 (SLC2A2), is responsible for diabetes-induced NTDs." (PMID 34439404, 2021). "The rs8192675 of the SLC2A2 gene correlates with a higher prevalence of diabetes symptoms, though this variation was not localized in SLC2A2 mice." (PMID 39535164, 2024). "Similarly, we observed enrichment of genes associated with the molecular genetics of type 2 diabetes (T2D) and Maturity Onset Diabetes of the Young (MODY; e.g. Hnf1a, Hnf4a, Slc2a2, Gck) in βTC6." (PMID 28931935, 2017). "Co-treatment substantially reduced the diabetes-induced upregulation of Slc2a2, but not Slc5a1 and Slc5a2, mRNA levels when compared to all other diabetic arms." (PMID 27226136, 2016).
diabetes (continued). "As chow-fed Slc2a2+/− animals showed a mild age-related metabolic phenotype, we induced metabolic dysfunction using a 45% HFD and tested the effects of Metformin as they develop diet-induced insulin resistance and to better reflect the development of obesity-induced diabetes in the human population." (PMID 37717665, 2023). "SLC2A1, SLC2A2 and SLC2A5 gene expression in mid-jejunal mucosa was measured to investigate whether intestinal glucose transporters could be influenced by diabetes, diet and/or metformin-pioglitazone medication and as such have an effect on the postprandial plasma glucose concentrations." (PMID 34669714, 2021). "Therefore, it is unlikely to imagine that Slc2a2 is the diabetes suppressor." (PMID 27667715, 2016).
Hyperglycemia (132 papers, 2009 to 2026). An increased concentration of glucose in the blood. "On a population level, variants in the SLC2A2 gene have been associated with fasting hyperglycemia, transition to type 2 diabetes, hypercholesterolemia, and risk of cardiovascular diseases in genome-wide association studies (GWAs)." (PMID 32591906, 2020). "Double allele knockout of the mouse SLC2A2 gene resulted in severe hyperglycemia, low insulin, and high glucagon in the blood." (PMID 31540540, 2019). "GLUT2/SLC2A2 variants are predictive of hyperglycemia development, more specifically." (PMID 37892034, 2023). "Therefore, the downregulated PDX-1 and associated reduced SLC2a2 expression are coupled with hyperglycemia tolerance of β-cells." (PMID 36248064, 2022). "The up-regulation of Gcg and down-regulation of Slc2A2 in liver might be partly responsible for the hyperglycemia induced by dietary Se deficiency." (PMID 28763492, 2017). "Since Glut2 (encoded by SLC2A2) is involved in the lowering of blood glucose levels during hyperglycemia, through transporting glucose from blood into liver, it is reasonable to assume that elevated transcription or translation of this gene will lead to a more rapid decrease in blood glucose level." (PMID 27439361, 2016). "Therefore, the SLC2A2 variant we identified may be a novel variant related to hyperglycemia in the Korean population, and additional studies are needed to reveal that the novel variant has a functional association with the phenotypes of MetS." (PMID 35999587, 2022). "Reduced PDX-1 activity stimulates hyperglycemia and β-cell dysfunction and apoptosis, which is correlated to SLC2a2 and GCK down-expression." (PMID 36248064, 2022). "In Goto Kakizaki rats, an inbred diabetic rat model displaying hyperglycemia and an increased glucose intolerance, aging resulted in a progressive decrease of Slc2a2 expression, an accumulation of cytoplasmic GLUT2 protein and impaired GSIS." (PMID 32394191, 2020). "The reduction in Slc2a2 transcripts can be explained by either chronic hyperglycemia resulting from the high-fat diet or a direct fat-dependent regulation of Slc2a2 expression." (PMID 32394191, 2020). "The loss of function mutations in SLC2A2 presumably leads to reduced function or expression of GLUT2 in the pancreatic β-cell impairing insulin secretion, leading to hyperglycemia." (PMID 32877990, 2020). "When Slc2a2+/− male and female mice were crossed and transient hyperglycemia was induced in pregnant mice with glucose injection, Slc2a2+/− embryos were partially protected while Slc2a2−/− embryos were completely protected from hyperglycemia-induced neural tube defects." (PMID 37616226, 2023). "Secondly, in humans homozygous GLUT2 mutations manifest in postprandial hyperglycemia but symptoms are not comparable with the severe β-cell failure observed in the Slc2a2−/− mouse model." (PMID 32394191, 2020). "This could mean that changes in the transcription or translation of SLC2A2 might affect the abundance of its protein product (Glut2) as well as their efficiency of transporting glucose from blood to the liver during hyperglycemia." (PMID 27439361, 2016). "Research indicates that Akt1 is capable of regulating Slc2a2 transcription in liver tissues, strengthening the liver’s capacity to uptake glucose from the circulation, facilitating cellular energy metabolism, and optimizing glucose utilization efficiency, consequently diminishing hyperglycemia." (PMID 41517209, 2026). "However, when hsa-miR-193b-3p was overexpressed, we observed a decreasing trend in SLC2A2/GLUT2 expression, suggesting lower glucose uptake, which may contribute to hyperglycemia, a feature associated with the plasma increase in hsa-miR-193b-3p in humans." (PMID 36835287, 2023). "Under conditions of hyperglycemia and perturbed GSIS, the glucose transporter Slc2a2 is markedly downregulated, which correlates with an impaired insulin secretory response in both mice and rats." (PMID 34949756, 2021).
type 2 diabetes (70 papers, 2010 to 2025). "Genome-wide association studies indicate that SLC2A2 sequence variation associates with risk of fasting hyperglycaemia, progression to type 2 diabetes, hypercholesterolaemia and cardiovascular diseases." (PMID 32938474, 2020). "Consistent with this, GLUT2 knockout mice have abnormal feeding behaviour and mutations in the human SLC2A2 gene are associated with a preference for sugar feeding and type 2 diabetes." (PMID 32591905, 2020). "Candidate gene association studies have shown that SNPs in solute carrier family 2, member 2 (SLC2A2) are associated with beta-cell function, insulin action and higher risk of developing type 2 diabetes." (PMID 31737029, 2019). "Future research should focus on exploring possible pathways associated with the SLC2A2 variant in linking fasting glucose, type 2 diabetes and ischemic vascular damage." (PMID 23185617, 2012). "Polymorphisms of SLC2A2 have also been linked with increased risk of developing type 2 diabetes." (PMID 23341889, 2013). "GCKR, a hub gene identified simultaneously by the susceptibility variants of alcohol consumption and type 2 diabetes, has densely interacted with type 2 diabetes-related genes such as FTO and SLC2A2." (PMID 34830198, 2021). "We have previously reported that SNPs in the GLUT2 gene (Slc2a2) influence response to the main drug for type 2 diabetes." (PMID 32938474, 2020). "CACNA1A is a Calcium Channel, Voltage-Dependent, P/Q Type, Alpha 1A Subunit; SLC2A2 is a solute carrier family 2 (Facilitated Glucose Transporter); hsa04930 is pathway related to type 2 diabetes." (PMID 27984588, 2016). "SLC2A2 (which encodes glucose transporter 2 [GLUT2]) mediates the uptake of glucose into beta cells, is essential for GSIS and is associated with an increased risk for type 2 diabetes." (PMID 37311878, 2023). "A previous study found an association between SLC2A2 SNP rs5400 and an increased risk of type 2 diabetes but we are not aware of studies linking the SNP to type 1 diabetes." (PMID 31728565, 2020). "Moreover, the methylation level of genes related to type II diabetes mellitus was also prominently decreased, including Prkce, Prkcz, Adipoq, Tnf, Slc2a2, Prkcd, and Mapk10." (PMID 26881249, 2016). "For example, the pathway of the disease of type II diabetes mellitus, is correlated to tobacco smoking, and the genes involved are ADIPOQ, PIK3CA, and SLC2A2." (PMID 32455963, 2020).